DKK1 (dickkopf Wnt signaling pathway inhibitor 1)
Diseases named in the same sentence as DKK1 in open-access papers (continued):
Sharing a sentence is not in itself a finding about the gene and the disease.
esophageal cancer (28 papers, 2010 to 2025). A primary or metastatic malignant neoplasm involving the esophagus. "DKK1 upregulation was associated with the miR-33a-5p downregulation in esophageal cancer cell lines as well as in human specimens." (PMID 39795613, 2025). "In pancreatic and esophageal cancers, DKK1 can bind to its receptor cytoskeleton‐associated protein 4 (CKAP4) and then activate the PI3K–AKT pathway to promote tumor growth." (PMID 38525111, 2024). "CKAP4 (cytoskeleton-associated protein 4) was identified as Dickkopf1 (DKK1) receptor, which is correlated with prognosis in pancreatic, lung, and esophageal cancers, and the DKK1 signaling pathway was always activated during cancer cell proliferation." (PMID 31360146, 2019). "Several authors have documented that DKK1 was preferential expressed in hormone-resistant breast tumors that was associated with poor prognosis and had identified DKK1 as a serologic and prognostic biomarker for lung and esophageal carcinomas." (PMID 25144498, 2014). "Other biomarkers such as Dickkopf-related protein 1 (DKK1) could serve as a novel biomarker for improving risk stratification and treatment monitoring of patients with esophageal cancer." (PMID 36611908, 2022). "One study showed that DKK1 was overexpressed in patients with lung and esophageal cancer, leading to poor prognosis in these patients and also becoming a new target for immunotherapy." (PMID 36447119, 2023). "Overexpression of DKK-1 has also been detected in breast, lung, and esophageal carcinomas, especially in patients presenting with bone metastases." (PMID 38067123, 2023). "In order to understand the role of DKK1 in esophageal cancer, we analyzed blood samples of esophageal cancer patients for their DKK1 levels and retrospectively analyzed the clinicopathological data." (PMID 34638464, 2021). "Univariate and multivariate Cox analyses of DKK1 expression with overall survival (OS) among esophageal carcinoma (ESCA) patients." (PMID 34899842, 2021). "In conclusion, these data suggest a crucial role for DKK1 in esophageal carcinoma as a biomarker for treatment response and poor overall survival, which should be further evaluated in prospective studies to be implemented into clinical routine." (PMID 34638464, 2021). "DKK1 has been shown to increase the invasive potential of esophageal cancer and DKK1 antibodies have been used clinically as a target for passive immunotherapy." (PMID 26545120, 2015). "Moreover, due to the small number of cases, the diagnosis and clinical value of serum miR-33a-5p and DKK1 in esophageal cancer still need to be further verified by clinical practice." (PMID 34426559, 2021). "As the use of serum DKK1 (S-DKK1) is limited to research and not yet established in the clinical setting, we determined the mean S-DKK1 of our 91 patients suffering from esophageal cancer (EC) and 30 obesity patients who served as the healthy control before surgery." (PMID 34638464, 2021). "However, it has been shown that in several GI cancers, including esophageal cancer, DKK1 may act as an oncogene itself through Wnt-independent signaling pathways." (PMID 39795613, 2025). "Moreover, high serum level of DKK1 has been detected in patients with NSCLC and esophageal carcinoma where it was associated with tumor progression and poor outcome of these malignancies suggesting that DKK1 in these tumor malignancies may have an oncogenic role." (PMID 26353782, 2015). "Nonetheless, DKK1 was downregulated in negative lymph nodes of patients with esophageal cancer and pN1 compared with negative lymph nodes of pN0 patients." (PMID 39795613, 2025). "Stomach adenocarcinoma (STAD), thyroid carcinoma (THCA), HNSCC, lung squamous cell carcinoma (LUSC), liver hepatocellular carcinoma (LIHC), esophageal carcinoma (ESCA), colon adenocarcinoma (COAD), and cholangiocarcinoma (CHOL) all showed considerably higher DKK1 expression." (PMID 38376441, 2024).
esophageal cancer (continued). "In our study cohort, we observed a negative prognostic role of high DKK1 serum levels with respect to overall survival in esophageal cancer patients." (PMID 34638464, 2021). "Increased DKK1 serum concentrations have been observed in patients suffering from ESC, and high expression levels have been shown to be a prognostic biomarker for esophageal carcinomas." (PMID 25048826, 2014).
Osteopenia (26 papers, 2009 to 2025). Osteopenia is a term to define bone density that is not normal but also not as low as osteoporosis. "A deficiency in SIRT6 causes the hyperacetylation of H3K9 in the Dkk1 promoter, resulting in osteopenia." (PMID 37626845, 2023). "Overexpressing DKK1 in osteoblasts was found to decreased osteoblast numbers and in osteopenia, whereas DKK1 allele single deletion was associated with increased bone formation and bone mass in another murine model." (PMID 28628652, 2017). "Forced overexpression of DKK1 in OB causes osteopenia by disruption of the hematopoietic stem cell niche and its function." (PMID 28079119, 2017). "An independent association of OP/osteopenia with plaque formation was observed when independent predictors for both variables were considered, with low DKK1 levels being associated with both plaque formation and lower BMD levels." (PMID 25886059, 2015). "In the mice model, increased DKK1 levels were associated with osteopenia." (PMID 34373766, 2021). "The increased DKK-1 levels, especially in GD patients with osteopenia, are probably reflective of osteoblasts’ altered differentiation and activity, similar to elevated RANKL in GD patients with osteopenia." (PMID 36506070, 2022). "Transgenic mice overexpressing Dkk1 develop osteopenia, whereas mice haploinsufficient for Dkk1 exhibit high bone mass." (PMID 33420361, 2021). "In bone, DKK1 binds to Lrp6 also antagonizing the Wnt/β-catenin pathway, whereby over-expression of DKK1 results in osteopenia." (PMID 32668736, 2020). "Over–expression of DKK1 in mice shows that DKK1 markedly reduces osteoblast numbers and directly attenuates osteoblast matrix mineralization, resulting in osteopenia." (PMID 31197079, 2019). "Overexpression of Dkk1 resulted in a decrease in bone mass, leading to osteopenia, while increased bone formation and bone mass was observed in single allele Dkk1 knockout mice." (PMID 29776381, 2018). "Remarkably, we found that OIM induced a significant increase in DHS at the promoter of DKK1, a known competitive inhibitor of the WNT pathway whose expression is linked to osteopenia and bone metastasis." (PMID 26890492, 2016). "Forced overexpression of DKK1 in osteoblasts leads to osteopenia and inhibits fracture repair." (PMID 25788856, 2014). "In addition, antihormonal treatment-induced osteopenia may also have a significant impact on DKK-1 and sclerostin levels." (PMID 30116403, 2018). "First, while mice lacking one allele of Dkk1 display the expected high bone mass phenotype, Dkk2-deficient mice are characterized by reduced bone formation and osteopenia, thereby demonstrating that these two Krm2 ligands do not mediate the same effects on osteoblasts in vivo." (PMID 20436912, 2010). "Our assumption is in line with previous in vivo studies, showing that oral annatto TT supplementation prevented osteopenia induced by metabolic syndrome by reducing SOST and DKK1 levels, considered antagonist of the Wnt signalling pathway." (PMID 32629979, 2020).
ovarian carcinoma (26 papers, 2007 to 2025). A malignant neoplasm originating from the surface ovarian epithelium. "In ovarian cancer cells, cordycepin instigates Dickkopf-related protein 1 (DKK1)-associated autophagy by inhibiting the β-cyclin signalling pathway." (PMID 38953102, 2024). "Elevated levels of DKK-1 are also associated with advanced clinical stage and poor prognostic outcomes in gynaecological malignancies including ovarian cancer." (PMID 34174910, 2021). "Besides, the expression of DKK1 in the “cytokine production involved in immune response” pathway was also elevated in BRCA1-deficient ovarian cancer patients." (PMID 35517499, 2022). "DKK1 expression is often upregulated in ovarian cancer and has been associated with poor outcome." (PMID 24586866, 2014). "In contrast, patients with sarcoma and ovarian cancer who expressed high levels of DKK1 showed little effect on their OS." (PMID 38376441, 2024). "Recent findings have revealed overexpression of DKK1 in ovarian cancer and inhibition of WNT signaling." (PMID 40836974, 2024). "We compared our findings with other studies related to DKK1 and found similar phenomena in breast and ovarian cancers." (PMID 39107271, 2024). "On the other hand, we also detected the mRNA levels of DKK1 in BRCA1 knock-down ovarian cancer cell lines." (PMID 35517499, 2022). "Accordingly, ELISAs showed that the protein levels of DKK1 in the culture medium were decreased in two ovarian cancer cell lines." (PMID 33613114, 2021). "The DKK1 expression levels were downregulated in ovarian cancer tumors and correlated with FIGO stages, grades and disease-free survival." (PMID 33613114, 2021). "In summary, the expression levels of DKK1 were downregulated in ovarian cancer patients and correlated with FIGO stage, grade and disease-free survival." (PMID 33613114, 2021). "Briefly, lower expression of DKK1 was found in ovarian carcinoma and ovarian serous adenocarcinomas than normal tissue based on the Bonome and Yoshihara subdatasets." (PMID 33613114, 2021). "To investigate the role of DKK1 in ovarian cancer development, we determined the DKK1 expression level in ovarian cancer tissue versus normal tissue in the CSIOVDB and Oncomine databases." (PMID 33613114, 2021). "Overall, these data indicated that CA125, through attenuating DKK1 expression, modulates ovarian cancer cell migration." (PMID 33613114, 2021). "Namely, CA125 promotes the migration of ovarian cancer cells by reducing DKK1 expression and activating the SGK3/FOXO3 pathway." (PMID 33613114, 2021). "Our data showed that anti-MSLN can block the reduction of DKK1 mediated by CA125 in ovarian cancer cells." (PMID 33613114, 2021). "In this study, we found that CD83 associated with MAP3K7 and activated MAPK cascades to further regulate FOXO1/p21/CDK2/CCNB1 and STAT3/DKK1 signaling pathways, thus activating proliferation and spheroid formation of ovarian cancer cells." (PMID 32823589, 2020). "The increased STAT3 expression and attenuated wingless-type MMTV integration site family (WNT) antagonist DKK1 were observed in CD83-overexpressed ovarian cancer cells." (PMID 32823589, 2020). "Overexpression of DKK1 altered the immune microenvironment of ovarian cancer, leading to decreased CD8+ T cells and natural killer cells and a reduction of interferon-gamma (IFNy) expression on activated CD8+ T cells." (PMID 32560059, 2020). "In our study, DKKs and SFRPs were all upregulated in response to TET1 overexpression except DKK1, which is a similar result obtain by two other studies in colon and ovarian cancer." (PMID 31399111, 2019).
ovarian carcinoma (continued). "Our GRNI analysis suggests that E2F1 interacts with DKK-1 in the normal ovary, but that this interaction is lost in ovarian cancer." (PMID 22548828, 2012). "In ovarian cancer, the deadliest of the gynecological tumors, DKK1 overexpression provides a tumor-friendly microenvironment to inhibit the anti-tumor immune cell populations, which may have a leading role in combination immunoregulatory therapy." (PMID 35355709, 2022). "To dissect the effect of DKK1 in ovarian cancer, we analyzed several public databases." (PMID 33613114, 2021). "DKK1 decreased in ovarian cancer tissues at an advanced stage of disease progression." (PMID 33613114, 2021). "In our previous study, we examined whether CA125 promotes ovarian cancer cell migration and whether DKK1 reverses the ability of CA125 to induced migration." (PMID 33613114, 2021). "Anti-MSLN abrogated the DKK1 reduction and increased the apoptosis of ovarian cancer cells." (PMID 33613114, 2021). "However, our data revealed that although CA125 strongly decreased the expression levels of DKK1, the Wnt/β-catenin pathway was inactive in ovarian cancer cells." (PMID 33613114, 2021). "Moreover, CD83 functions through the activation of MAP3K7-MEK1/2-ERK1/2 cascades to further regulate downstream FOXO1/p21/CDK2/CCNB1 and STAT3/DKK1 signaling pathways, thus activating proliferation and spheroid formation of ovarian cancer cells, respectively." (PMID 32823589, 2020). "Our results further show the mechanisms underlying the stimulation of proliferation and stemness of ovarian cancer cells by CD83, involving interaction with MAP3K7 and activation of MAPK signaling pathway, as well as downstream FOXO1/p21/CDK2/Cyclin B1 and STAT3/DKK1 cascades." (PMID 32823589, 2020). "Beyond ICB, recent evidence suggests that the Wnt inhibitor DKK1 may serve as an immunotherapeutic target in ovarian cancer." (PMID 32560059, 2020). "Experimental restoration of TET1 repression in ovarian cancer cells could also inhibit the growth of ovarian cancer cells by reversing DNA-methylation-associated silencing of SFPR2 and DKK1—two endogenous inhibitors of WNT signaling." (PMID 31426393, 2019). "Although the exact role of DKK1 in the aggressive nature of ovarian cancer is unknown, it has been proposed as a useful marker of disease and may be one of the many factors contributing to high-grade serous ovarian cancer." (PMID 24586866, 2014). "Two genes (TMEPAI and DKK1) were studied based on their role in metastasis in ovarian cancer." (PMID 24586866, 2014). "DKK-1 is a secreted glycoprotein that acts as a specific antagonist of WNT signaling; up-regulation of this pathway due to down-regulation of DKK-1 has been implicated in several cancers, and inhibition of WNT signaling by DKK-1 inhibits ovarian carcinoma cell proliferation." (PMID 22548828, 2012). "DKK1 plays a role in driving the CDDP-resistant phenotype, and knocking down DKK1 can make NSCLC cells and ovarian cancer cells sensitive to CDDP." (PMID 37835450, 2023). "Our data demonstrated that the DKK1 expression level was downregulated by elevated CA125 and was related to migration induced by CA125 in ovarian cancer cells in vitro." (PMID 33613114, 2021). "To determine the relationship between CA125 and DKK1 expression levels in ovarian cancer, we added CA125 to the culture medium of ovarian cancer cells." (PMID 33613114, 2021). "In epithelial ovarian cancer, research has revealed that ten-eleven translocation 1 (TET1) inhibits cell migration and invasion by upregulating DKK1 28, which is partly consistent with our study." (PMID 33613114, 2021).
ovarian carcinoma (continued). "High expression of CA125 on ovarian cancer cells results in release of the fragment free CA125, which binds to the mesothelin on the surface of ovarian cancer cells to reduce DKK1 expression." (PMID 33613114, 2021). "To validate our in vitro results, we determined the clinical implication of ITF2 and DKK1 expression in NSCLC and ovarian cancer patients." (PMID 32224864, 2020). "By siRNA-mediated knockdown of DKK1 in NSCLC and ovarian cancer cells, the colony forming capacity and/or cell survival upon cisplatin treatment was reduced significantly." (PMID 26353782, 2015). "Developing theranostic approaches that capitalize on DKK1 and RSPO1 as therapeutic targets may pave the way for personalized treatment strategies tailored to the unique molecular profiles of ovarian cancer patients." (PMID 40836974, 2024). "Our results demonstrated that CA125 via the MSLN/DKK1/SGK3/FOXO3 pathway accelerates cell migration, and targeting mesothelin may potentially be utilized in ovarian cancer therapy." (PMID 33613114, 2021). "DKK1 protein expression did not change (p > 0.05) in two ovarian cancer cell lines stimulated with CA125 and anti-MSLN compared to the unstimulated cell line." (PMID 33613114, 2021). "Similarly, the observed upregulation of Wnt signaling inhibitors such as Dkk1 and Notum in patients with BRCA2mt ovarian cancer may also very well be a negative feedback response." (PMID 39028933, 2024). "Moreover, DKK1 is also highly expressed in CDDP-resistant cells in non-small cell lung cancer and ovarian cancer." (PMID 37835450, 2023).
liver cancer (23 papers, 2008 to 2025). An epithelial or non-epithelial malignant neoplasm that arises from the liver. "As EpCAM is a marker of liver cancer stem cells, we further evaluated the expression of genes encoding EpCAM and DKK-1 using EpCAM+/− cells sorted from Huh7 cells." (PMID 35269944, 2022). "To investigate the role of the key molecule DKK1, we constructed DKK1-overexpressing liver cancer cell lines, hepa and H22." (PMID 39505867, 2024). "We then conducted preliminary functional experiments to explore the role of DKK1 in liver cancer cells." (PMID 39505867, 2024). "Histone H3-Thr11 phosphorylation and Lys9 acetylation synergistically promoted DKK1 gene transcription in liver cancer." (PMID 37861491, 2023). "DKK4 suppresses cell invasion, whereas DKK1 promotes invasion and metastasis in serous ovarian cancer and liver cancer." (PMID 27806330, 2016). "Some studies have confirmed that the combined detection of serum CA724 and CA19-9 has high specificity and sensitivity in the diagnosis of gastric stromal tumor, and studies have also reported that serum DKK1 has an obviously high expression in patients with primary liver cancer." (PMID 36276284, 2022). "DKK-1 levels were lower in patients with liver cirrhosis (p = 0.002) and showed a strong correlation with total radiologic tumor size (r = 0.593; p < 0.001) and with Barcelona Clinic Liver Cancer stages (p = 0.032)." (PMID 36230730, 2022). "Similarly, DKK1 induced a very significant increase (p <0.01) in the expression of TGF-β1 in both liver cancer cell lines with a very pronounced increase in TGF-β1 secretion of more than 300%." (PMID 31568519, 2019). "Numerous glycoproteins have been confirmed to screen AFP-negative liver cancer in clinical studies, including Golgi protein 73 (GP73), dickkopf-1 (DKK1), angiopoietin-like protein 2 (ANGPTL2), and haptoglobin (Hp)." (PMID 33889548, 2021). "Our results showed that DKK1 does not have an antiproliferative effect on our liver cancer cell lines." (PMID 31568519, 2019). "In liver cancers, FZC18 immunostaining negatively correlates with Wnt/β−catenin signaling and with the protein expression of the β−catenin-regulated gene GS, consistently with the suppression of GS synthesis by DKK1 in mice carrying an APC disruption." (PMID 18382662, 2008).